OXT (oxytocin/neurophysin I prepropeptide)
Diseases named in the same sentence as OXT in open-access papers (continued):
Sharing a sentence is not in itself a finding about the gene and the disease.
postpartum depression (13 papers, 2010 to 2026). A type of clinical depression that occurs after childbirth. "Research has shown that the neuropeptide OXT and the female hormone estrogen are implicated in maternal behavior and postpartum depression." (PMID 31251738, 2019). "Furthermore, the reduced level of OXT observed during pregnancy and parturition is closely associated with the development of postpartum depression." (PMID 31251738, 2019). "The same group also reported that one of the SNPs interacted with early life adversity to predict variation in breastfeeding duration and depression, as genetic variation in OXT rs2740210 and early adversity was associated with postpartum depression and breastfeeding duration." (PMID 27617302, 2015). "Interestingly, serum OXT levels during pregnancy were associated with depressive symptoms in early pregnancy or postpartum and may serve as a predictive target for postpartum depression." (PMID 38017588, 2023). "The present study has proposed an investigation into gene–environment interaction effects for the occurrence of postpartum depression and OXT SNP genotypes of rs2740210; rs4813627 and OXTR SNP genotypes of s237885." (PMID 40076753, 2025). "As far as we know, no studies have assessed the association between the OXTR rs2740210, OXT rs4813627, or OXTR rs237885 polymorphisms and the development of postpartum depression." (PMID 40076753, 2025). "We suggest it is now timely to investigate whether OXT agonists/analogs may benefit some women with postpartum depression in a randomized controlled trial." (PMID 38959890, 2024). "Another study of postpartum depression used the Edinburgh postnatal depression scale (EPDS) to assess the risk of postpartum depression and showed that plasma OXT plasma OXT concentrations were lower in the high-risk group compared with subjects in the low-risk group for postpartum depression." (PMID 38017588, 2023). "Thus, in a post-partum depression rat model induced by gestation restraint stress, local injection of OXT into the paraventricular nucleus reversed depressive-like behaviors and reduced also the high plasma corticosterone level." (PMID 32485966, 2020). "Together these studies suggest that OXT is important for the decreased stress reactivity observed in lactation and general reward-related behaviour, and as such represent an important factor in the aetiology of postpartum depression (PPD)." (PMID 27713275, 2010). "Moreover, they suggest that altered OXT system activity may be involved in postpartum depression (see OXT in the peripartum period section)." (PMID 27713275, 2010). "In addition, these results may differ across populations and cultures, suggesting that the interaction effects between postpartum depression and OXT/OXTR SNP genotypes may also depend on the population; therefore, there may be other different target genes to be considered." (PMID 40076753, 2025). "The mRNA expression of OXT in the PVN has been reported to decrease in rats receiving continuous restraint stress during gestation, which is a postpartum depression model." (PMID 32733584, 2020). "The occurrence of postpartum depression was shown only among mothers with the CC genotype of OXT_rs2740210 not in those with AA/AC genotypes, supporting the main hypothesis of our study." (PMID 40076753, 2025). "The results obtained showed that polymorphisms in OXT, but not in OXTR, could predict the onset of postpartum depression, and also, could be used as a maternal instrumental care screening tool." (PMID 40076753, 2025). "However, postpartum depression did not mediate the gene-environment effects of OXT SNPs on maternal care." (PMID 27617302, 2015).
anxiety disorder (11 papers, 2012 to 2025). A category of psychiatric disorders which are characterized by anxious feelings or fear often accompanied by physical symptoms associated with anxiety. "Due to the correlation between OXT, attachment and stress response as well as the evidence of other animal and human studies, it is hypothesized that the etiology of anxiety disorders, particularly those with a social component, may be associated with an imbalance of the endogenous OXT system." (PMID 33902711, 2021). "This study aims to examine associations between peripheral OXT, sAA, and CORT release, and fronto-limbic rsFC in response to psychosocial stress in adolescents with depressive and anxiety disorders, compared to healthy controls." (PMID 41372844, 2025). "In summary, the present study is expected to make an important contribution to research on the endogenous stress reactivity in adolescents suffering from anxiety disorders and the significant role of OXT in the etiology of psychiatric disorders." (PMID 33902711, 2021). "With the purpose of a better understanding of the linkage between dysregulation of the endogenous OXT system and the etiology of anxiety disorders, the present study aims to investigate three questions as main outcome objectives." (PMID 33902711, 2021). "In our sample, state anxiety derived from the STAI questionnaire was neither associated with OXTR methylation rates nor salivary OXT measurements, neither in HC nor in FND patients." (PMID 39726815, 2025). "It is hypothesized, that the endogenous OXT system of children and adolescents (11–18 years of age) suffering from a clinically diagnosed anxiety disorder is dysregulated." (PMID 33902711, 2021).
mental disorder (7 papers, 2015 to 2023). A disease that has its basis in the disruption of mental process. "Moreover, OXT is being tested as a therapeutic tool to alleviate social dysfunction in mental disorders for which ES is a risk factor." (PMID 31404254, 2019). "However, perturbed functioning of AVP and OXT has recently been linked to a variety of mental disorders with social dysfunction, and they are suggested to have therapeutic relevance for treatment of disorders with social dysfunction as well." (PMID 31404254, 2019). "One interesting neuromodulatory system in the context of BED is the oxytonergic system as the regulation of the neuropeptide oxytocin (OXT) is thought to play a role in a broad spectrum of mental disorders." (PMID 36042529, 2022). "This review summarizes findings on the impact of different OXT and AVP receptor polymorphism on social cognition and behaviors, and on some of the most common mental disorders associated with deficits in social function." (PMID 26858594, 2015). "Likewise, previous studies have also found a potential association between altered OXT and AVP plasma levels with the risk of suffering mental disorders in pregnancy, especially PPD." (PMID 37373400, 2023). "Alterations in OXT, AVP and their receptors are related to different obstetric complications and mental disorders related to pregnancy like postpartum depression (PPD) or preeclampsia." (PMID 37373400, 2023). "The evidence on the effects of intranasal applications of OXT and AVP on clinical populations expressing a mental disorder is relatively sparse, and echoes the mixed findings for healthy population." (PMID 26858594, 2015).
type 2 diabetes (7 papers, 2011 to 2025). "Through Mendelian randomization we demonstrate potentially causal effects of FGF21 and HAVCR1 on risk for type 2 diabetes, of HPGDS on BMI, and of OXT on risk for lacunar stroke." (PMID 40225784, 2025). "In conclusions, taken together the present results provide evidence that OXT is closely related to the course and treatment of type 2 diabetes." (PMID 22997507, 2012).
Hypertension (6 papers, 2018 to 2025). The presence of chronic increased pressure in the systemic arterial system. "Both AVP and OXT neurons demonstrate structural and functional adaptions to physiological challenges such as dehydration, changes in physiological state such as pregnancy, and pathophysiological states such as hypertension or hyponatremia." (PMID 37858270, 2023).
metabolic syndrome (6 papers, 2019 to 2025). A cluster of metabolic risk factors for CARDIOVASCULAR DISEASES and TYPE 2 DIABETES MELLITUS. "Furthermore, the higher the serum OXT level, the higher the risk of metabolic syndrome." (PMID 37509007, 2023). "However, men with metabolic syndrome had higher OXT levels than those without metabolic syndrome." (PMID 35525976, 2022).
osteoporosis (6 papers, 2013 to 2023). A condition of reduced bone mass, with decreased cortical thickness and a decrease in the number and size of the trabeculae of cancellous bone (but normal chemical composition), resulting in increased fracture incidence. "OXT is also implicated in bone tissue homeostasis; in fact, functional disequilibria in OXT was observed in bone-related pathologies like osteoporosis." (PMID 37445991, 2023). "Thus, OXT is potentially useful to advance embryonic stem cell development to reverse osteoporosis and repair infarction damaged cardiac tissue." (PMID 24967304, 2013).
post-traumatic stress disorder (6 papers, 2018 to 2023). An anxiety disorder precipitated by an experience of intense fear or horror while exposed to a traumatic (especially life-threatening) event. "The main results showed that the presence of ET and post-traumatic stress disorder (PTSD) is strongly associated with reductions in endogenous OXT, and also that the acute effects of OXT administrations in individuals with ET tend to be anxiolytic only in less severe forms." (PMID 29545749, 2018).
prostate carcinoma (6 papers, 2017 to 2025). A carcinoma that arises from epithelial cells of the prostate gland. "We used OXT, because this hormone stimulates the activation of Gαi proteins and also, we previously found that OXT induces migration of prostate cancer cells by activating Gαi2." (PMID 32575572, 2020). "In addition to proliferation, OXT stimulates cellular migration in human endothelial and prostate cancer cells, but inhibits migration in head and neck squamous cell carcinoma cells." (PMID 36263085, 2022). "Previously, we showed that Gαi2 plays a critical role in oxytocin (OXT) and EGF signaling to induce cell migration in prostate cancer cells." (PMID 40141305, 2025). "Previously, we found that endogenous Gαi2 is essential for cell migration and invasion in prostate cancer cells in response to different stimuli, such as EGF, OXT, TGFβ1 and SDF-1α." (PMID 32575572, 2020).
social anxiety disorder (6 papers, 2011 to 2025). "In contrast, a positive correlation was found between OXT levels and symptom severity in patients with social anxiety disorder, indicating that excessive attention may raise peripheral OXT levels." (PMID 27536785, 2016).
bipolar disorder (5 papers, 2016 to 2025). A disorder of the brain that causes unusual shifts in mood, energy, activity levels and the ability to carry out day-to-day tasks. "Our previous report highlighted dysregulation of OXT on striatocortical functional connectivity (FC) in bipolar disorder (BD) patients." (PMID 40886241, 2025). "From this view point, overactivity and the attention sthenia of bipolar disorder and adolescent irritable depression (which includes TRDIA) may be associated with OXT." (PMID 27536785, 2016). "Considering the meanings of high serum levels of OXT in individuals with TRDIA, we suspect that TRDIA patients with high serum OXT levels might develop bipolar disorder." (PMID 27536785, 2016). "Thus, serum OXT might be a possible biomarker for differentiating the symptoms of ADHD, bipolar disorders and irritable adolescent depression, because their symptoms are similar regarding irritation, impulsivity and inattentiveness, especially in pediatric to adolescent sufferers." (PMID 27536785, 2016).
Borderline personality disorder (5 papers, 2019 to 2025). A personality disorder characterized by impulsive behavior and unpredictable, capricious mood. "Surprisingly, very little research has been done to assess potential therapeutic effects of OXT in borderline personality disorder." (PMID 31404254, 2019).
Cognitive impairment (5 papers, 2020 to 2024). Abnormal cognition is characterized by deficits in thinking, reasoning, or remembering. "Recently, we reported for the first time in the literature that OXT reversed Aβ-induced cognitive impairment." (PMID 37887270, 2023). "As a result, the effects of OXT and OXTR variants can be observed in humans from prenatal development to adulthood, as well as in daily social interactions seen in individuals with social cognition impairment such as ASD." (PMID 38191308, 2024). "Taken together, OXT alleviates cognitive impairment in AD-model animals." (PMID 37887270, 2023). "With an unmet clinical need for HD biomarkers, both OXT CSF and plasma levels may give some indication of the status of social cognitive deficits in HD." (PMID 36187357, 2022). "The purpose of this study was to examine the effect of OXT on behavior in relation to social and non-social cognitive impairment in HFD-fed mice." (PMID 32719656, 2020). "Furthermore, our research has indicated that the OXT pathway may be affected in patients with ALS due to atrophy of the left a‐sHyp subunit, leading to psychiatric symptoms, such as cognitive impairment." (PMID 38887187, 2024).
heart failure (5 papers, 2020 to 2025). Inability of the heart to pump blood at an adequate rate to meet tissue metabolic requirements. "OXT also has cardioprotective benefits in heart failure models and after experimental myocardial infarction, however, it has not yet been linked to heart regeneration." (PMID 36247002, 2022).
Sepsis (5 papers, 2016 to 2023). Sepsis is defined as life-threatening organ dysfunction caused by a dysregulated host response to infection. "OXT has been shown to have anti-inflammatory effects and a possible protective role against sepsis by limiting organ damage associated with this pathology." (PMID 37525237, 2023). "In wound healing and sepsis-induced animal models, subcutaneous injections of OXT were shown to diminish the immune and inflammatory response." (PMID 32819381, 2020). "However, few studies evaluated its relationship with sepsis, despite a relationship between OXT and sepsis or other inflammatory states has been suggested." (PMID 37525237, 2023).
Alzheimer disease (4 papers, 2022 to 2023). A progressive, neurodegenerative disease characterized by loss of function and death of nerve cells in several areas of the brain leading to loss of cognitive function such as memory and language. "For example, we recently reported that OXT recovered impairment of spatial memory in Alzheimer’s disease (AD) model mice established by intracerebroventricular injection of β-amyloid protein (Aβ), commonly used to mimick the pathogenesis of AD." (PMID 37971993, 2023).
COVID-19 (4 papers, 2021 to 2026). A disease caused by infection with severe acute respiratory syndrome coronavirus 2. "Among these connections, ADHD exerts a promotion effect on COVID-19 through the inhibition of OXT and PON1 and the promotion of CRP, AR, and TNF." (PMID 38066446, 2023). "OXT system is impaired in most patients with PWS and the high plasmatic levels of OXT (possibly due to overcompensation of a brain deficit) in patients with PWS could play a protective role against COVID-19." (PMID 34289876, 2021). "OXT seems to carry special functions in immunologic defense: it suppresses neutrophil infiltration and inflammatory cytokine release, activates T-lymphocytes, and antagonizes negative effects of angiotensin II and other key pathological events of COVID-19." (PMID 34289876, 2021). "Indeed, OXT, a neuropeptide produced in the hypothalamic paraventricular nucleus and supraoptic nucleus, is an immune-regulating neuropeptide, which has recently emerged as a candidate for treatment and prevention of COVID-19." (PMID 34289876, 2021). "Literature-based data mining and construction of the molecular pathways revealed a total of seven genes connecting ADHD with COVID-19, including CRP, PON1, AR, OXT, IL6, TNFSF12, and IL10.." (PMID 38066446, 2023). "By the depressing expression of OXT, ADHD may increase the propensity of an individual to develop severe COVID-19 and to be hospitalized." (PMID 38066446, 2023). "Pathway analysis identified several immunity-related genes that may link ADHD to COVID-19, including CRP, OXT, IL6, PON1, AR, TNFSF12, and IL10." (PMID 38066446, 2023). "The OXT system is defective in most individuals with PWS, and high plasma levels of OXT in people with PWS (perhaps due to overcompensation of a brain impairment) may provide a protective role against COVID-19." (PMID 35632654, 2022). "In addition to the young age of our adults’ cohort, another hypothesis explaining the absence of severe COVID-19 in adults with PWS could be the beneficial role of oxytocin (OXT)." (PMID 34289876, 2021).
Glucose intolerance (4 papers, 2011 to 2022). Glucose intolerance (GI) can be defined as dysglycemia that comprises both prediabetes and diabetes. "We found that OXT treatment significantly improved glucose intolerance and fasting blood insulin levels of mice, and this effect was observed without involving body weight change since the experimental duration was only an overnight period." (PMID 23700406, 2013). "Data revealed that [Ser4, Ile8]-OXT treatment reduced the magnitude of STZ-induced glucose intolerance." (PMID 23700406, 2013). "Using the same STZ-induced diabetic model and the same drug treatment paradigm, we found that [Ser4, Ile8]-OXT treatment significantly prevented STZ-induced glucose intolerance, and this effect was accounted for by the improvement on insulin secretion rather than body weight." (PMID 23700406, 2013).